IL10 (interleukin 10)
Diseases named in the same sentence as IL10 in open-access papers (continued):
Sharing a sentence is not in itself a finding about the gene and the disease.
anemia (continued). "The capacity of the host to induce IL-10 immediately after the induction of a prominent pro-inflammatory immune response mediated via M1 cells determines whether pathology/anemia develops/is alleviated or not." (PMID 29497418, 2018). "While severe anaemia is an important cause of death in P. chabaudi infection of several strains of mice, anaemia peaks in both IL-10−/− and WT mice at day 10 post-infection, and not during the time frame when most IL-10−/− animals are succumbing to infection (days 7–9 post-infection)." (PMID 27557867, 2016). "Hemophagocytosis is reported in this model of MAS where splenic hemophagocytosis was observed following blocking of IL-10 and the role of IFN-γ to mediate anemia was shown to be not necessary for fulminant TLR-9–induced MAS and hemophagocytosis." (PMID 38558807, 2024). "Furthermore, not all field studies support the hypothesis that IL-10 controls severe anaemia." (PMID 35464430, 2022). "In addition, blood levels of anemia-related inflammatory cytokines, including IFN-γ, TNF-α, IL-6 and IL-10, were not affected by the daily administration of 2500 mg TIMEx/kg body weight in both sexes." (PMID 34040996, 2021).
ovarian carcinoma (118 papers, 2012 to 2025). A malignant neoplasm originating from the surface ovarian epithelium. "Vorinostat is a histone deacetylase inhibitor (HDACi) that suppresses HDAC6 expression, thereby disrupting the ARID1A6488delG/HDAC6/IL-10 signaling pathway implicated in endometriosis-associated ovarian carcinoma (EAOC)." (PMID 40330466, 2025). "IL-10 was also associated with ovarian cancer cell migration and the worst disease-free survival of ovarian cancer patients." (PMID 37322531, 2023). "In human ovarian cancer and glioma cancer, tumor-associated Tregs trigger macrophages to secrete IL-10 and IL-6, which activate STAT3 and induce B7-H4 transcription." (PMID 35410218, 2022). "Recent studies also propose that increased serum levels and peritoneal cavity levels of both IL-6 and IL-10 are associated with factors of worse prognosis in ovarian cancer patients." (PMID 32138790, 2020). "High serum levels of IL-10 have previously been detected in patients with ovarian cancer, and are consistently associated with advanced progression and poor prognosis in multiple cancer types." (PMID 31552179, 2019). "Higher concentrations of IL-10 were associated with more advanced clinical stages of ovarian cancer, which was also reported by Cho and Shih." (PMID 28376925, 2017). "Among these OPG, IL-10, and leptin in the ascites of ovarian cancer patients were shown to be associated with shorter progression-free survival." (PMID 24093089, 2013). "Out of 120 cytokines analyzed OPG, IL-10, and leptin was found to be associated with worst prognosis in ovarian cancer patients." (PMID 24093089, 2013). "Notably, IL-10 in ascites has been associated with both the migration of ovarian cancer cells and, in some cases, longer survival in patients receiving cell-free and concentrated ascites reinfusion therapy (CART)." (PMID 40361187, 2025). "Our natural epigenetic treatments downregulated the secretion of IL-10, associated with induction of proliferation, migration, and immunosuppression in ovarian cancer, by more than 70%, an effect comparable to that obtained by treatment with the synthetic compound Pano." (PMID 37509102, 2023). "High IL-10 levels (>24 pg/mL in ascites fluid), detected in all three huPDX models, are associated with significantly shorter progression-free survival in patients with ovarian cancer." (PMID 36860657, 2023). "In this context, pDCs have also been associated with poor prognosis in ovarian carcinoma patients by inducing IL-10-producing CD8+ Treg cells and inhibition of T cell proliferation, resulting in an induction of angiogenesis through production of TNF and IL-8, as reported in human ovarian cancer." (PMID 35406451, 2022). "However, their results failed to support an association between selected polymorphisms at IL-1α, IL-β, IL-6, IL-10, or IL-18 gene and increased risk of ovarian cancer in USA." (PMID 34582655, 2021). "The high immunosuppressive activity of IL-10 may partially explain the higher pro-tumor activity of type II OC cells and confirm different progression mechanisms underlying in type I and type II ovarian cancer." (PMID 28589429, 2017). "The microenvironment of ovarian cancer tumors is rich in IL-6, IL-10, and CSF-1, which promotes M2 polarization and the accumulation of M2 macrophages." (PMID 39981173, 2025). "This aligns with the predominance of M2-like macrophages in ovarian cancer, which foster immune suppression via IL-10, TGF-β, and VEGF signaling." (PMID 40330466, 2025). "The immune system, which can act against tumors, often supports tumor development in the ovarian cancer microenvironment through immunoevasion, which is influenced by cytokines such as IL-6, IL-10, and TGF-β." (PMID 40362280, 2025). "The immune tumor suppressive marker interleukin-10 has been shown to be elevated in cancer, specifically in ovarian cancer." (PMID 39199610, 2024).
ovarian carcinoma (continued). "This study aims to correlate interleukin-10 levels in the ascites and sera of ovarian cancer patients to correlate with cancer-related data and outcomes." (PMID 39199610, 2024). "Cytokines such as IL-2, IL-5, IL-6, IL-8, and IL-10, both pro-inflammatory and anti-inflammatory, have been measured in serum, intracystic fluid, and peritoneal fluid in endometriomas and ovarian cancers." (PMID 38337827, 2024). "Interleukin-10 (IL-10) has been shown to be present at high levels in the ascites of ovarian cancer (OC) patients; however, little is known about its prognostic value." (PMID 39199610, 2024). "A differential diagnosis can be attempted between benign serous ovarian cysts, endometriomas, and ovarian cancers using the levels of IL-10 and TNF-alpha." (PMID 38337827, 2024). "Studies suggest endometriosis as a contributing factor in ovarian cancer, with cytokines IL-2, IL-5, IL-6, IL-8, and IL-10 detected in serum, intra-cystic fluid, and peritoneal fluid in endometriomas and ovarian cancer patient samples." (PMID 39596309, 2024). "IL-6, IL-10, TNF-α, IFN-γ, TNF-α have been substantiated as directly linked to poor outcomes in epithelial ovarian cancer (EOC) patients." (PMID 38279997, 2024). "A large number of cytokines have been reported as elevated in ovarian cancer ascites samples including IL-6, IL-8, IL-10, IL-15, IP-10/CXCL10, MCP-1/CCL2, Mip1α/CCL3, Mip1β/CCL4, MDC, and VEGF." (PMID 36860657, 2023). "The invasiveness of ovarian cancer cells is induced by various cytokines such as IL-10 and IL-6, which are secreted by the TAMs that have M2-like phenotypes and express CD206 and arginase-1 (ARG1)." (PMID 36757936, 2023). "In vitro data indicate that ovarian cancer cells release N-acetylaspartate, which acts synergistically with IL-10 to polarize macrophages to an M2 with high expression of glutamine synthetase." (PMID 35565348, 2022). "Serum and ascites levels of Il-10 are also correlated to a higher grade and prognosis in ovarian cancer." (PMID 35565348, 2022). "Previous studies have shown that in ovarian cancer CD14+ cells can suppress T cell proliferation via IL-10." (PMID 34727230, 2022). "The conclusion was further supported by a previous finding that IL-10 level was significantly reduced by MDSCs depletion in ovarian cancer-bearing mice." (PMID 35004667, 2021). "Supporting this in␣vitro model, in silico data and the analysis of ascitic fluid isolated from ovarian cancer patients prove that an M2‐like macrophage phenotype, IL‐10 release, and NAA levels positively correlate with disease stage." (PMID 34260142, 2021). "In our study, we found that FPR2 played an auxoaction on the secretion of IL-10 and IL-4 in ovarian cancer cells and the induction of M2 macrophage polarization." (PMID 34930387, 2021). "IL-10 is a cytokine whose levels have been shown to be elevated in the tumour microenvironment and blood of tumour-bearing mice as well as ovarian cancer patients." (PMID 34930387, 2021). "In advanced epithelial ovarian cancer, high concentrations of IL-6, IL-10, growth-related oncogene-alpha, and vascular epithelial growth factor (VEGF) were associated with cell proliferation of human ovarian cancer cells." (PMID 32283687, 2020). "IL-10 levels are reported to be increased in serum and ascites from patients with ovarian cancer, with higher levels in advanced disease." (PMID 33075095, 2020). "Tregs from ovarian carcinoma patients express high levels of CCR5, and treatment with conditioned medium from ovarian carcinoma stem-like cells increases their expression of IL-10 and MMP-9." (PMID 32630699, 2020). "CD163 and CD206 mRNA expression is also associated with IL-10 levels in ascites, which indicate a shorter relapse free survival (RFS) in patients with ovarian cancer." (PMID 32774171, 2020).
ovarian carcinoma (continued). "IL10, IL6, IL6ST, and macrophage scavenger receptor 1 (MSR1; CD204) were positively correlated with ovarian cancer patients in the high-risk group using heatmap analyses of the signature with the immune-related genes." (PMID 33381581, 2020). "On the one hand, CD4+ T cells accumulating in tumors often belong to the Foxp3 expressing regulatory T cell subset, which can be induced by TAMs through IL-10 release as demonstrated in tumor tissues of ovarian cancer patients." (PMID 30853959, 2019). "Our results suggest that CSCs have an intrinsically higher immuno-suppressive program, driving CD206 expression in M0 macrophages to a larger extent than bulk unsorted ovarian cancer cells, evident also by the increased IL10 gene expression in CSCs." (PMID 31324218, 2019). "Characterization of MV derived from sera of head and neck squamous cell carcinoma (HNSCC) patients and ascites from ovarian carcinoma patients demonstrates increased expression of IL-10, TGFβ, and Fas ligand (FasL)." (PMID 31681327, 2019). "We have shown that MSCs and MSCs CM induced a significant increase in the level of IL-4 AND IL-10 in the 4 ovarian cancer cell lines." (PMID 31351482, 2019). "For example, ascites-derived vascular endothelial growth factor (VEGF), IL-6, IL-10, TGF-β, and arachidonic acid played a prominent role in the polarization of immunosuppressive tumor-associated macrophages (TAMs) in ovarian cancer ascites." (PMID 30477198, 2018). "Cho as well as Sheu and Shih found that high expression of HLA-G/sHLA-G and a high level of IL-10 in the micro-environment of ovarian cancer contribute to an aggressive course of the disease." (PMID 28376925, 2017). "This conclusion is supported by the observation that the ascites concentrations of IL-10, highly predictive of a poor survival of ovarian cancer was consistently and dramatically increased in subgroup A versus subgroup B patients." (PMID 28327095, 2017). "These molecules were upregulated on CD8+ T cells by IL-6 and IL-10, present in ovarian carcinoma ascites, as well as by tumor-infiltrating DCs." (PMID 28275576, 2017). "Ovarian cancer patients presented with significantly higher median serum concentrations of IL-10 than other study subjects." (PMID 28376925, 2017). "Ovarian cancer patients presented with significantly higher median serum concentrations of IL-10 and TNF-alpha than other study subjects." (PMID 28376925, 2017). "Median difference between peritoneal fluid and serum concentrations of IL-10 was the highest in ovarian cancer patients, followed by women with endometrioma and those with serous ovarian cysts." (PMID 28376925, 2017). "In agreement with the established function of deregulated STAT3 in ovarian cancer, IL-10, IL-6, and LIF were confirmed as components of the signaling network established by tumor cells and TAMs." (PMID 27215396, 2016). "A profile of cytokines in the ascites of epithelial ovarian cancer patients identified enhanced expression of many factors including angiopoietin, IL-6, IL-8, IL-10 MCP-1, and RANTES." (PMID 27852034, 2016). "Stage III ovarian cancer patients have higher frequencies of IL-10+ B cells than stage II patients, both in the peripheral blood and ascites." (PMID 27331871, 2016). "Kohno and colleagues have reported anti-angiogenic and tumor suppressive effects of IL-10 in ovarian cancer cells." (PMID 27157642, 2016). "In the ascites of ovarian cancer patients, the frequencies of IL-10+ B cells are also positively correlated with the frequencies of CD4+Foxp3+ Tregs." (PMID 27331871, 2016). "A trend toward higher concentration of IL-10 was observed in the serum of ovarian cancer patients compared to those with benign cysts; however, the difference was not significant." (PMID 25999622, 2015). "A trend toward a higher concentration of IL-10 was observed in serum of ovarian cancer patients compared to those with benign cysts." (PMID 25999622, 2015).
ovarian carcinoma (continued). "Release of multiple inflammatory cytokines into the plasma, including IFNγ, IL-1β, IL-6, IL-8, IL-10, TNFα, PlGF, and HSP90B1, is frequently associated with epithelial ovarian cancers (EOC)." (PMID 26858849, 2015). "TGF-β1, vascular endothelial growth factor and IL-10 were expressed in 100, 74.69 and 54.96% of malignant tissues of epithelial ovarian cancer, respectively, suggesting that these cytokines have immunosuppressive roles." (PMID 25624918, 2015). "The elevation of serum norepinephrine and IL-10 levels induced by chronic stress was observed to promote the growth of ovarian carcinoma in mouse models." (PMID 25624918, 2015). "In the current study, we performed a comparative analysis on mRNA expression of CXCR3, CXCL-10 (IP-10), CXCR4, CXCL-12 (SDF-1α), IL-4 (interleukine-4) and IL-10 in tissues of benign and malignant ovarian tumors by the qRT-PCR method." (PMID 25999622, 2015). "We compared the mRNA expression of CXCR3, CXCL-10, CXCR4, CXCL-12, IL-4, and IL-10 in tissues of benign and malignant ovarian tumors by qRT-PCR method and evaluated serum IL-10 and CA-125 content of these patients by ELISA during one year." (PMID 25999622, 2015). "The concentration of inflammatory cytokines such as IL-1β, IL-6, IL-8, IL-10 was shown to be significantly higher in the ascites of ovarian cancer patients compared to that present in the serum, and correlated with poor prognosis and response to therapy." (PMID 24093089, 2013). "In a phase 1/1b trial (NCT02009449), one ovarian cancer patient and 22 pancreatic cancer patients were recruited to evaluate the safety and efficacy of pegilodecakin (pegylated IL-10) as monotherapy, and the results showed that patients did not have obvious clinical responses." (PMID 38279997, 2024). "Additionally, several studies have confirmed that IL-10 release mediates ICB resistance in ovarian cancer." (PMID 39301023, 2024). "Therefore, inhibition of IL-10 by our epigenetic treatments can target the growth and metastasis of ovarian cancer cells." (PMID 37509102, 2023). "Similar to the effects observed following treatment with Pano, EGCG and I3C downregulate the secretion of IL-10, an immunosuppressive factor in ovarian cancer ascites correlated with proliferation and metastasis, as well as maintenance of the tumorigenic microenvironment." (PMID 37509102, 2023). "IL-10 also induces immunosuppressive B7-H4 expression on ovarian cancer TAMs." (PMID 35565348, 2022). "Apart from confirming the association between of high levels of TGFBI and poor prognosis, Steitz and colleagues found that ovarian cancer cell migration was stimulated by soluble mediators produced by macrophages from HGSOC ascites as well as IL10-stimulated monocyte-derived macrophages." (PMID 34561272, 2021). "It has been reported that blocking IL-10/IL-10R could decrease the infiltration of MDSCs in ascites of ovarian cancer-bearing mice." (PMID 35004667, 2021). "Interleukin 10 regulates Toll-like receptor-mediated dendritic cell activation in ovarian cancer." (PMID 34109184, 2021). "Moreover, IL-6 and IL-10 released by blood monocytes-derived TAMs activate the pro-survival STAT3 signaling in ovarian cancer cell lines and cancer cells isolated from patients’ ascites, keeping them alive." (PMID 32456078, 2020). "Another suppressive mechanism through which IL-10 could take part in the pathogenesis of ovarian cancer, is through mediation of the expression of the immune check-point inhibitor ‘PD-1' in a STAT3-dependent manner." (PMID 32931721, 2020). "They found that various ovarian cancer cell lines treated with cisplatin or carboplatin induced differentiation of macrophages into an M2-like phenotype characterized by elevated production of IL-10 and enhanced activation of STAT3 signaling factor." (PMID 32456078, 2020). "Furthermore, high levels of IL-10 at the ascites of ovarian cancer patients was shown to increase the migration of tumour cells, thereby enhancing tumour progression." (PMID 32931721, 2020).